LIMK1 (LIM domain kinase 1)
Diseases named in the same sentence as LIMK1 in open-access papers (continued):
Sharing a sentence is not in itself a finding about the gene and the disease.
tumor (continued). "We found that LIMK1 mRNA was upregulated in all tumor stages, and patients with high levels exhibited lower overall survival." (PMID 33482809, 2021). "Correlation analysis indicated LIMK1 mRNA expression was correlated with tumor purity and immune infiltrates." (PMID 34149814, 2021). "The LIMK1 protein expression was assessed by the Clinical Proteomic Tumor Analysis Consortium (CPTAC) and the Human Protein Atlas." (PMID 34149814, 2021). "Heterogeneous expression for CFL-1, SSH1 and LIMK1 were detected when tumor tissues were paired with adjacent normal samples." (PMID 33482809, 2021). "In the context of the role of LIMK1 in OS tumour progression, some studies have shown that different drugs act on OS cells via LIMK1." (PMID 34944050, 2021). "Above findings demonstrated that the anti-tumor activity of dasatinib was mediated by LIMK1 in PDX mice model." (PMID 33344441, 2020). "Dasatinib remarkably inhibited the expression of Ki67, p-LIMK1/2, and p-cofilin protein in tumor tissues from dasatinib-treated group as compared to vehicle treated group." (PMID 33344441, 2020). "Then we examined the expression of Ki67, p-LIMK1/2, and p-cofilin in xenograft tumor sections using the IHC analysis." (PMID 33344441, 2020). "From our studies, PDX tumors exhibiting higher p-LIMK1 expression showed more dramatic decrease in tumor volume as well as related IHC biomarker staining when treated with dasatinib." (PMID 33344441, 2020). "Then, Pearson correlation analysis indicated the positive correlation between DANCR and LIMK1 in xenograft tumour models." (PMID 31038266, 2019). "A homolog of the LIMK family, LIMK1, which was overexpressed throughout tumor progression, served as a competitive inhibitor of LIMK2 via β-catenin nuclear translocation." (PMID 29970879, 2018). "The study further demonstrated that DADS had a significant anticancer effect, and LIMK1 was a potential target molecule of DADS for inhibiting tumor cell migration and invasion." (PMID 28358024, 2017). "Comparison with the other groups indicated that tumor growth with the overexpression of LIMK1 was faster, but the tumor growth decreased significantly after DADS treatment." (PMID 28358024, 2017). "Compared with the empty vector and SW480 groups, tumor growth in LIMK1 silencing in DADS treatment groups was slower (P < 0.05)." (PMID 28358024, 2017). "The role of protein kinase LIMK1 in tumor invasion and metastasis is still under discussion, similarly to its role in cell migration." (PMID 28025492, 2016). "LIMK1 expression scores greater than or less than 2 were used to divide normal and tumor tissue specimens into high-expression and low-expression groups." (PMID 26871290, 2016). "In this study, we reveal that LIMK1 expression is correlated with tumor differentiation, invasion depth, clinical stage, lymph node metastasis, and poor prognosis." (PMID 26871290, 2016). "Using a TMA with 20 patient matched samples of tumour core and rim regions, we demonstrate that LIMK1 and pCFL are more highly expressed at the tumour rim and periphery than in the core." (PMID 25237832, 2014). "On average 43% of the cells stained positively for LIMK1 in the periphery compared to only 12% of cells that were positive in the tumour core (p<0.05)." (PMID 25237832, 2014). "We observed a correlation between positive pCFL and positive LIMK1 expression in the tumour periphery, (Fischer's Exact Test, p=0.0001)." (PMID 25237832, 2014). "Previous studies have shown that LIMK1 plays a central and important role in tumor cell invasion and metastasis." (PMID 24858712, 2014). "LIMK1 was the most downregulated gene from this analysis and has been previously reported to have a role in tumor cell invasion and metastasis." (PMID 24858712, 2014). "We tested several low and high doses of BMS-5 and Cucurbitacin I and observed no cytotoxic effect on NHAs at low doses suggesting our small molecule inhibitors act specifically on tumor cells expressing LIMK1 and pCFL." (PMID 25237832, 2014).
tumor (continued). "We found that the tumor suppressive effects of miR-143 on NSCLC cells were partially reversed by overexpression of Limk1." (PMID 25003638, 2014). "Using a well-characterized tissue microarray of 20 GBM patients for which a tumour core and a matched tumour periphery sample were available we undertook immunohistochemical (IHC) analysis of LIMK1 and pCFL." (PMID 25237832, 2014). "Abnormal expression of LIMK1 and LIMK2 is implicated in various malignancies, and is known to be important in tumor manifestation and malignancy." (PMID 25593987, 2014). "Our study shows increased expression of both proteins in the same tumor samples, which suggests a clinical relevance of overexpression of both LIMK1 and MT1-MMP." (PMID 21219645, 2011). "Nevertheless, these data support the interesting concept that nuclear LIMK1 contributes to the tumor-promoting effects of total cellular LIMK1." (PMID 21682918, 2011). "By analyzing an ESCC tissue microarray (TMA) consisting of 208 tumor tissues and 152 matched adjacent normal tissues, high expression of LIMK1 (52.40%, 109/208) was observed in human ESCC tissues compared with paired normal tissues (21.71%, 33/152) (P < 0.001)." (PMID 40476449, 2025). "Consequently, elevated H19 levels facilitate cancer progression through the disinhibition of LIMK1, contributing to tumor advancement." (PMID 40781643, 2025). "Indeed, if some authors reported that mp57 inhibits LIMK1 activity by delocalizing and trapping LIMK1 in the nucleus, others described that, in tumor cells, hp57 promoted the cytoplasmic activity of LIMK1." (PMID 39456957, 2024). "LIMK1 might trigger the chemoattraction of macrophages by tumour cells upon CSF-1 release and PKCζ activation, leading to tumour invasion and metastasis." (PMID 36899941, 2023). "This insinuates that LIMK1 knockdown could curtail tumor cell proliferation, while WRN knockdown could stimulate it." (PMID 37828981, 2023). "LIMK1 promotes tumor growth and tumor angiogenesis by increasing uPA expression." (PMID 37894409, 2023). "Dasatinib also inhibited the growth of patient-derived tumor in mice by targeting LIMK1." (PMID 36559193, 2022). "LIMK1 can enhance cell migration and promote tumor cell metastasis." (PMID 35265128, 2022). "A CSRS scoring system including four CS genes (MYC, DLX2, EPHA3, and LIMK1) was constructed, which could distinguish the survival outcome, tumor microenvironment (TME) status, and ICB treatment response of patients with different CSRS score." (PMID 36106335, 2022). "In CRC lacking SMAD4, BMPR2 can bind to LIM domain kinase 1 to activate the Rho/Rho-associated protein kinase (ROCK) pathway to promote tumor invasion and metastases." (PMID 35805024, 2022). "Then tumor weight was detected after the mice were euthanized, the results showed that knockdown circ-LIMK1 could inhibit the volume and weight of tumor, and tumor volume and weight were lower after treatment with DDP compared with PBS." (PMID 36304135, 2022). "LIMK1 plays an important role in the regulation of tumor cell division and invasiveness." (PMID 35265128, 2022). "The expression of circ-LIMK1 was up-regulated in DDP-resistant tumor tissues and cells." (PMID 36304135, 2022). "LIMK1 is another downstream factor of the Rho signaling, which is essential to tumor metastasis." (PMID 34486491, 2021). "However, there are contradictory results and data regarding the expression of cofilin in tumor cells, effects of dephosphorylation of cofilin and the expression level of LIMK1 on cell migration and invasion." (PMID 33614640, 2021). "Bioinformatic analysis revealed that LIMK1 expression was upregulated in all tumor stages." (PMID 33482809, 2021). "A significant worse overall survival rate was observed for patients with high levels of LIMK1 in all tumor stages, early stage, and late stage (P < 0.001, P < 0.01, and P < 0.01, respectively), indicating that high level LIMK1 was an unfavorable prognostic indicator in patients with CRC." (PMID 33482809, 2021).
tumor (continued). "To determine whether the correlation between luteolin efficacy and Ki‐67, p‐Limk1/2 and p‐cofilin expression that we observed in vitro could be recapitulated in vivo, we performed immunohistochemistry (IHC) analysis in the tumour samples." (PMID 33982869, 2021). "Indeed, in a recent study, Li and Coll examined 56 patients and determined an increase in LIMK1 protein levels in tumour tissues, as compared to the expression measured in adjacent healthy tissues." (PMID 34944050, 2021). "In addition, it has been reported that Limk1 was involved in the cancer development including tumor invasion or cell apoptosis." (PMID 33062725, 2020). "LIMK1 plays critical role in tumour cell invasion and metastasis in various cancers." (PMID 33126409, 2020). "Silencing the expression of LIMK1 could enhance the inhibitory effect of DADS on tumor growth, whereas the overexpression of LIMK1 could weaken the inhibitory effect of DADS on tumor growth." (PMID 28358024, 2017). "However, it is known that LIMK1 enhances tumor proliferation and metastasis in vitro and in vivo and is also involved in actin cytoskeleton dynamics for cancer invasiveness." (PMID 27625789, 2016). "Furthermore, mice treated with LIMK1 + DADS or LIMK1-miR exhibited reduced or increased tumor volumes, respectively, in contrast to those treated with DADS alone." (PMID 26871290, 2016). "However, there is a body of evidence that LIMK1 can influence the metastatic phenotype of tumor cells via regulation of cofilin activity, and the controversial effects of LIMK1 expression on migration and metastasis of cancer cells require an explanation." (PMID 28025492, 2016). "Furthermore, we found that PAK4 bound to LIM kinase 1 (LIMK1) directly and activated it via phosphorylation, which is required for tumor cell motility and invasion." (PMID 25975262, 2015). "Therefore, a balance between LIMK1 and cofilin levels is suggested to determine migration and invasion in tumour cells." (PMID 26592552, 2015). "In this study, we demonstrate that decreased miR-143 expression is a characteristic molecular signature in NSCLC and that miR-143 may function as a tumor suppressor by directly targeting LIM domain kinase 1 (Limk1)." (PMID 25003638, 2014). "Overexpression of Limk1 attenuated the tumor suppressive effects of miR-143 in NSCLC cells." (PMID 25003638, 2014). "Furthermore, suppression of LIMK2 in human fibrosarcoma cells or expression of a dominant negative LIMK1 in an animal model of tumor invasion, limited cell migration and efficiency to form dense colonies without affecting cell proliferation rate or viability." (PMID 24093776, 2013). "Thus, there are likely other, yet uncharacterized LIMK1 pathways that are distinctly affected by nuclear or cytoplasmic LIMK1 that contribute to the differential tumor promoting effects observed in vivo." (PMID 21682918, 2011). "We speculate that a threshold is reached in our system of LIMK1-mediated activation of FAK/paxillin/Src/AKT/Erk signaling as it contributes to tumor growth." (PMID 21682918, 2011). "Finally, tumor xenograft assays in female nude mice injected with MDA-MB-435 cells over-expressing LIMK1 resulted in tumors that were larger, more vascularized, and more likely to metastasize to the liver and lungs, compared to controls." (PMID 21682918, 2011). "Because LIM-domain proteins often function as nuclear scaffolds that can participate in transcription events, one possibility is that nuclear LIMK1 may mediate tumor promoting events via a direct contribution to transcription control." (PMID 21682918, 2011). "Within the cytoplasm, LIMK1 may mediate tumor progression via effects on p57Kip2 or serum response factor (SRF), both of which are thought to be directly regulated by cytoplasmic LIMK1, and both of which are known to influence tumor biology." (PMID 21682918, 2011).
tumor (continued). "Although all tumor samples exhibited positive cytoplasmic staining for LIMK1 in the luminal cells a propensity of increased intensity of LIMK1 staining and higher Gleason Scores could be noted." (PMID 17559677, 2007). "Our studies imply that the concentration of LIMK1 needs to be tightly regulated for proper cell cycle progression and that up regulation of LIMK1 may contribute to tumor progression through altered cell cycle pattern and chromosomal defects." (PMID 17559677, 2007). "Additionally, LIMK1 may influence immune cells within the tumor microenvironment, contributing to immune evasion." (PMID 40367093, 2025). "Moreover it has been shown that both H19 and LncROR can be transferred between cells via exosomes, leading to the increased activation of LIMK1 and TGFβ, respectively, in neighboring cells and thereby contributing to the spread of chemoresistance across the tumor microenvironment." (PMID 40781643, 2025). "Furthermore, LIMK1 may promote angiogenesis, thereby supporting tumor growth and metastasis by enhancing blood supply." (PMID 40367093, 2025). "Animal experimental results showed that silencing LIMK1 could reduce tumor size." (PMID 35265128, 2022). "However, it is possible to suggest that LIMK1 could coordinate proliferation and dissemination of tumor cells by both microtubule disassembly and actin polymerization." (PMID 33482809, 2021). "Indeed, targeting LIMK1 could inhibit not only the growth of primary tumours by acting on the control of OS cell proliferation but also the metastatic development by acting on the capacity of OS cells to migrate and invade." (PMID 34944050, 2021). "Notable metastatic nodules could be found in the lungs of tumor-burden mice injected with Hs578T/Control, PL-BC-05/Control, or Hs578T/sh Lnc-408/LIMK1 and PL-BC-05/KO Lnc-408/ectopic LIMK1, compared with mice injected with Hs578T/sh Lnc-408 and PL-BC-05/KO Lnc-408." (PMID 34079084, 2021). "Limk1 could enhance the tumor cell proliferation and invasion by the MMP or p21-related pathway." (PMID 33062725, 2020). "In addition, the expression of DANCR and LIMK1 was investigated in xenograft tumours by qRT‐PCR." (PMID 31038266, 2019). "Thus, we hypothesized that the tumor biology would also be impacted by both cytoplasmic and nuclear LIMK1." (PMID 21682918, 2011). "Furthermore, increased expression of LIMK1 in stromal cells in close proximity to the tumor areas in majority of the tumor samples may have a functional significance in phenotypic changes associated with advanced tumors." (PMID 17559677, 2007). "Given the important role of LIMK1 and CDK5 in tumor metastasis, the LIMK1 inhibitor BMS‐5 and CDK5 inhibitor Dinaciclib were employed to evaluate the potential of targeted therapy." (PMID 40476449, 2025). "Based on these findings, we proposed a combined therapeutic strategy of simultaneously targeting LIMK1 and CDK5 for the treatment of tumor metastasis, especially in ESCC." (PMID 40476449, 2025). "Collectively, these data suggest that upregulation of LIMK1 and CDK5 activates β‐catenin, promoting tumor metastasis and correlating with poor prognosis in ESCC." (PMID 40476449, 2025). "After that, five tumor antigens (ALOX15B, HS3ST2, PIGR, ZMYND15, and LIMK1) were identified to be candidates for the mRNA-based vaccine development, all of which were correlated with survival time of PRCC patients and the degree of APC infiltration." (PMID 36836593, 2023). "Five tumor antigens, including ALOX15B, HS3ST2, PIGR, ZMYND15 and LIMK1, were identified for PRCC, which were correlated with patients’ prognoses and infiltration levels of APCs." (PMID 36836593, 2023). "Taken together, LIMK1/cofilin is a crucial downstream signaling pathway of Rac1/PAK1 for regulating the rearrangement of actin cytoskeleton and lamellipodia extension of tumor cells." (PMID 37049739, 2023).
tumor (continued). "Taken together, five tumor antigens (ALOX15B, HS3ST2, PIGR, ZMYND15, and LIMK1), with potentially provocative effects on immunological functions, were identified and considered as eligible candidates for anti-PRCC mRNA vaccine development." (PMID 36836593, 2023). "One study has demonstrated that DEPDC1B can promote tumor cell invasion and migration by activating the Rac1/PAK1/LIMK1/cofilin pathway." (PMID 37049739, 2023). "In accordance with these data, studies using bladder, prostate, and gastric models have also correlated CFL-1 and LIMK1 expression pathways with the EMT program, as well as tumor initiation and metastatic colonization in breast model." (PMID 33482809, 2021). "To confirm the results obtained by bioinformatic analysis, we evaluated CFL-1, LIMK1, and SSH1 mRNA levels by RT-qPCR using tumor tissues from patients with CRC paired with adjacent normal tissues in a clinical cohort." (PMID 33482809, 2021). "CFL-1, LIMK1 and SSH1 mRNA/protein levels were assessed by real-time PCR and immunohistochemical analyses using normal adjacent and tumor tissues obtained from a clinical cohort of CRC patients." (PMID 33482809, 2021). "Protein-coding gene LIM Domain Kinase 1 (LIMK1) is upregulated in various tumors and reported to promote tumor invasion and metastasis." (PMID 34149814, 2021). "LIMK1 expression was upregulated (P < 0.0001) whereas CFL-1 and SSH1 were downregulated (P < 0.0001) in all tumor stages when compared with normal tissues." (PMID 33482809, 2021). "The protein levels of LIMK1, p-cofilin, cofilin, p-CREB, CREB, MMP2, ITGB1, and COL1A1 in mouse tumor tissues were consistent with the metastatic potential of the tumor in mice." (PMID 34079084, 2021). "LIMK1 is a central regulator of cytoskeletal dynamics, LIM kinases promote the proliferation and survival of tumor cells, and LIM kinase inhibitors can affect microtubule organization and mitosis of tumor cells." (PMID 34868397, 2021). "We have successfully applied the pONE vector set for expression of the following human proteins: the tumour suppressor RASSF1A and the protein kinases Aurora A and LIMK1." (PMID 31887188, 2019). "LIMK1 has only one known physiological substrate: CFL1, a small protein that is required for tumor cell movement." (PMID 30873211, 2019). "The tumor suppressor Nischarin interacts with a number of signaling proteins such as Integrin α5, PAK1, LIMK1, LKB1, and Rac1 to prevent cancer cell migration." (PMID 29415725, 2018). "LIMK1, which shares a strong homology with LIMK2, promotes tumor proliferation and metastasis in various tumors, including CRC." (PMID 29970879, 2018). "Our results demonstrate that both miR-200b-3p and miR-429-5p play a tumor-suppressive role in TNBC via a previously unreported target, LIMK1, which is involved in cellular proliferation and motility." (PMID 29156719, 2017). "Although several studies have reported that p57 can interact with LIM domain kinase 1 (LIMK1) to affect actin cytoskeleton dynamics, the role of cytoplasmic p57 in the regulation of tumor cell invasion is unclear." (PMID 26271467, 2015). "The suppression of Nischarin and LKB1 in these cells resulted in increased phosphorylation of PAK1 and LIMK1, and upregulation of Cyclin D1 and CDK4 expression, resulting in enhanced cell migration and tumor growth." (PMID 25695373, 2015). "Forced overexpression of miR-143 inhibited tumor growth and metastasis of NSCLC cells partially through targeting Limk1." (PMID 25003638, 2014). "Towards this end, we queried if LIMK1 and LIMK2 had prognostic value in a clinically annotated dataset (REpository of Molecular BRAin Neoplasia DaTa/REMBRANDT)." (PMID 25237832, 2014). "A positive correlation in the nuclear expression (staining) of LIMK1 and MT1-MMP in grade 3 and grade 4 tumors, which increased from 20% (grade 3 tumors) to 40% (LIMK1) and 45%(MT1-MMP)(grade 4 tumors) of the tumor samples stained, was also noted." (PMID 21219645, 2011).